MORC2 (MORC family CW-type zinc finger 2)
Diseases named in the same sentence as MORC2 in open-access papers (continued):
Sharing a sentence is not in itself a finding about the gene and the disease.
breast carcinoma (continued). "A similar example is the novel oncogene MORC2 (MORC family CW-type zinc finger 2), that has been found at high levels in breast cancer promoting metastatic progression." (PMID 33643916, 2020). "Findings presented here show that MORC2 promotes breast cancer invasion and metastasis, and the PRD domain is essential for the metastasis-promoting properties of MORC2 through interacting with CTNND1." (PMID 29228664, 2017). "To do this, we first examined the protein expression levels of endogenous MORC2 in normal mammary epithelial cell lines MCF10A and HBL100, and breast cancer cell lines MCF-7, T47D, SK-BR-3, BT474, MDA-MB-231, MDA-MB-468, Hs578T, and HCC1937." (PMID 29228664, 2017). "As one of the hallmarks of breast cancer is its ability to invade and metastasize, we next sought to determine the impact of MORC2 protein and its PRD domain on the invasive and metastatic capacity of breast cancer cells." (PMID 29228664, 2017). "MORC2 then interacts with the transcription factor c-Myc and is recruited to the LDHA promoter to control the expression of LDHA, which is responsible for the migration of breast cancer cells." (PMID 37892209, 2023). "O-GlcNAcylated MORC2 governs the expression of TGF-β1 target genes connective tissue growth factor (CTGF) and snail family transcriptional repressor 1 (SNAIL) and is crucial for breast cancer progression." (PMID 34974534, 2022). "We further showed that adriamycin (doxorubicin), a TOP2 poison by stabilizing the TOP2‐DNA covalent complex, has no evidential effects on MORC2 protein levels in breast cancer cells." (PMID 35522895, 2022). "In human breast cancer cells, PARP1 was revealed to mediate PARylation of MORC2 in DNA damage sites following DDR, which stimulated the ATPase and chromatin remodeling activities of MORC2 and protected the cell from death." (PMID 33194676, 2020). "Induced expression of wild-type MORC2 did not significantly affect cell proliferation and cell-cycle progression, but promoted breast cancer cell migration and invasion in vitro and metastatic lung colonization in vivo." (PMID 29228664, 2017). "Thus, whether the metastasis-promoting activity of MORC2 and the interaction between MORC2 and CTNND1 could apply to other breast cancer subtypes remain to be addressed in the future." (PMID 29228664, 2017).
gastric cancer (13 papers, 2015 to 2025). A primary or metastatic malignant neoplasm involving the stomach. "Taken together, the reciprocal expression of low C/EBPα and high MORC2 is associated with maintaining the different differentiation status of gastric cancer." (PMID 30644437, 2019). "Western blot results indicated that MORC2 S677A mutation attenuated the phosphorylation of MORC2 on serine 677 in Flag-MORC2/SGC-7901 cells (an exogenous MORC2 stable expression gastric cancer cell line) compared with wild-type MORC2 (MORC2-WT)." (PMID 25888627, 2015). "Our recent research found an association between MORC2 and gastric cancer." (PMID 30644437, 2019). "Furthermore, high expression of PAK1 and phosphorylation of MORC2 appear to be associated with poor prognosis of clinical gastric cancer." (PMID 25888627, 2015). "It has been reported that DNA methylation predominantly regulated CA9 expression in gastric cancer, while histone modifications, mediated by MORC2 and HDAC4, have been documented to control CA9 transcriptional activation through histone H3 deacetylation." (PMID 38177154, 2024). "For example, overexpression of MORC2 promoted the proliferation and invasion of gastric cancer (GC) cells and hepatocellular carcinoma (HCC) cells." (PMID 37692502, 2024). "Further, they also discovered that MORC2 enhances gastric cancer cell proliferation by controlling cell cycle progression via p21 suppression." (PMID 37892209, 2023). "Then, we found that the phosphorylation of MORC2 at Ser-677 (MORC2-S677A) by p21-activated kinase 1 (PAK1) promotes gastric cancer cell proliferation and tumorigenesis." (PMID 34839357, 2021). "We have been dedicated in determining the exclusive role of MORC2 in gastric cancer, and we discovered its transcriptional repressor role in gastric cancer." (PMID 34839357, 2021). "We observed that MORC2 can bind to target promoters and repress their transcription, which is crucial in cell proliferation and survival regulation, eventually leading to gastric cancer progression." (PMID 34839357, 2021). "Remarkably, high levels of MORC2 expression are correlated with an aggressive phenotype of clinical gastric cancer and shorter overall survival of patients." (PMID 34839357, 2021). "Most notably, the high expression of MORC2 is correlated with an aggressive phenotype of clinical gastric cancer and shorter overall survival of patients." (PMID 30644437, 2019). "Conversely, the increased C/EBPα expression was shown in adjacent normal tissues and well-moderate differentiation gastric cancer tissues, along with the decreased MORC2 expression (down panel)." (PMID 30644437, 2019). "Following, we determined the expression of MORC2 and C/EBPα in gastric cancer tissues and matched adjacent normal tissues from 40 cases gastric tumor patients by performing immunochemical staining of MORC2 and C/EBPα." (PMID 30644437, 2019). "Taken together, these findings suggest that MORC2 overexpression attenuate C/EBPα-medicated inhibition of cell proliferation and tumorigenesis in gastric cancer via sumoylation." (PMID 30644437, 2019). "More importantly, phosphorylation of MORC2 correlates positively with PAK1 expression in clinical gastric cancer." (PMID 25888627, 2015). "To further study the role of MORC2 phosphorylation in gastric cancer, we analyzed levels of PAK1and phosphorylated MORC2, by western blotting, in 68 pairs of gastric cancers and matched adjacent normal gastric tissue samples." (PMID 25888627, 2015). "To better understand the correlation between them, we divided tumor samples into two groups on the basis of PAK1 amounts (cut off at the median score), and studied the differences of p-MORC2 expression with clinical gastric cancer." (PMID 25888627, 2015). "Statistical analysis revealed MORC2 expression negatively correlated with p21 expression (P = 0.038) in gastric cancer tissues." (PMID 26098774, 2015).
gastric cancer (continued). "To show the correlation between MORC2 and p21 in gastric cancer samples, we tested the expressions MORC2 and p21 in freshly frozen gastric cancer tissues and matched adjacent normal tissues from 68 gastric tumor patients." (PMID 26098774, 2015). "MORC2-mediated down-regulation of p21 in turn promoted cell cycle progression in gastric cancer cells." (PMID 26098774, 2015). "Here, we found that MORC2-mediated p21 expression plays a role in cell cycle progression, cell proliferation and tumorigenicity of gastric cancer cells." (PMID 26098774, 2015). "Consistent with observations at the cellular level, 29% (20 of 68) of the gastric cancer patients with MORC2 overexpression examined were in p21 down-regulation by western blot, and we got similar results in immunochemical staining." (PMID 26098774, 2015). "Taken together, overexpression of MORC2 contributes to cell cycle progression and proliferation of gastric cancer cells." (PMID 26098774, 2015). "In order to confirm the role of MORC2 in gastric cancer cells, colony formation assays were performed with Flag-MORC2/SGC-7901 cells and shRNA-MORC2/BGC-823 cells." (PMID 26098774, 2015). "There was a strong positive correlation between PAK1 and phosphorylation of MORC2 expression in gastric cancer samples." (PMID 25888627, 2015). "Notably, MORC2 phosphorylation on serine 739 in its CTD region by PAK1 kinase increases its recruitment to DNA damage sites and causes proliferation of gastric cancer cells." (PMID 40593625, 2025). "Moreover, the increased MORC2 expression negatively correlates with the decreased C/EBPα, which was also shown in the differentiation status of gastric cancer samples." (PMID 30644437, 2019). "Meanwhile, the result also suggest that MORC2 may have a relation to metastasis in clinical gastric cancer which will be studied in our future." (PMID 30644437, 2019). "Moreover, overexpression of MORC2 in clinical gastric cancer was also found to predict shorter overall survival of patients (P = 8.81 × 10−8)." (PMID 30644437, 2019). "In addition, we studied the correlation between MORC2 expression and clinicopathological characteristics in 210 gastric cancer samples." (PMID 30644437, 2019). "Moreover, the striking correlation between the decreased C/EBPα expression and the increased MORC2 expression was also observed in the poor differentiation status of gastric cancer tissues." (PMID 30644437, 2019). "Our research indicated that MORC2 promoted gastric cancer cell proliferation and tumorigenesis." (PMID 30644437, 2019). "Collectively, our data indicate that p21 is a novel MORC2 target gene and its expression repression may be at least partially owing to MORC2 overexpression, which contributes to gastric cancer development." (PMID 26098774, 2015). "Therefore, we here, established, for the first time, that there was a relationship between PAK1 and MORC2 in gastric cancer." (PMID 25888627, 2015). "MORC2 was phosphorylated in 71% (30 of 42) of gastric cancer with overexpressed PAK1 patients." (PMID 25888627, 2015). "Taken together, MORC2 phosphorylation contributes to tumorigenesis of gastric cancer cells." (PMID 25888627, 2015). "Therefore, MORC2-mediated p21 repression is involved in HDAC1 modification in gastric cancer cell lines." (PMID 26098774, 2015). "Thus, our findings provide important evidence to show the role of MORC2 phosphorylation in gastric cancer in vivo." (PMID 25888627, 2015). "Thus, the results indicate that phosphorylation of MORC2 mainly promotes gastric cancer cell cycle transition from G1 to S." (PMID 25888627, 2015). "Further study of MORC2 may provide promising new therapeutic targets for gastric cancer." (PMID 30644437, 2019). "Similarly, MORC2 represses p21 in gastric cancer cells by recruiting HDAC1 to the p21 promoter." (PMID 29329290, 2018). "Moreover, the role of MORC2 in gene transcription has been documented in gastric cancer cells." (PMID 29228664, 2017).
gastric cancer (continued). "Furthermore, MORC2 negatively correlates with p21 expression in clinical gastric cancer." (PMID 26098774, 2015). "Furthermore, MORC2 negatively correlates with p21 expression in gastric cancer samples, suggesting that MORC2 might be as a potential therapeutic target for cancer." (PMID 26098774, 2015). "Thus, we speculate that MORC2 may participate in gastric cancer progression and act as a potential therapeutic target for cancer." (PMID 26098774, 2015). "Interestingly, a recent study documented that MORC2 regulates cell differentiation of mouse myoblasts and human gastric cancer cells through enhancing SUMOylation of transcription factor C/EBPα 35, but whether MORC2 itself is regulated by SUMOylation and its functional consequence remain unknown." (PMID 36793866, 2023). "Statistical analysis revealed p-MORC2 expression positively correlated with PAK1 expression (p = 0.007) in gastric cancer tissues, which are consistent with our findings that overexpression of PAK1 upregulated p-MORC2 in gastric cell lines." (PMID 25888627, 2015). "The correlation of MORC2 and the PAK1 pathway has also demonstrated in clinical studies showing that higher levels of PAK1 expression and phosphorylated MORC2 correlates with shorter overall survival and poor prognosis of clinical gastric cancer." (PMID 34839357, 2021). "In gastric cancer, HSF1 could promote GC cell proliferation, migration and invasion by directly interacting with MORC2 and binding to the enhancer of ArgBP2." (PMID 30326922, 2018). "The specificity and reactivity of the antibody were verified with or without λ-PPase in BGC-823 cells (an endogenous MORC2 relatively high expression gastric cancer cell line) and gastric cancer tissues." (PMID 25888627, 2015). "In addition, our data presented here show that high expression of phosphorylated MORC2 and PAK1 correlates postively with clinical poor prognosis of gastric cancer." (PMID 25888627, 2015). "The function of MORC2 in gastric cancer has not yet been investigated." (PMID 25888627, 2015).
spinal muscular atrophy (12 papers, 2018 to 2025). A motor neuron disease that affect the muscles, and characterized by muscle weakness and atrophy resulting from progressive degeneration and irreversible loss of the anterior horn cells in the spinal cord (i.e., lower motor neurons) and the brain stem nuclei. "Dominant variants in MORC2 can cause spinal muscular atrophy and the Charcot-Marie-Tooth (CMT) neuromuscular disease." (PMID 40593625, 2025). "MORC2-associated disorders range from CMT2Z to symptoms resembling spinal muscular atrophy (SMA), with early onset and predominantly proximal muscle involvement." (PMID 39464795, 2024). "Occasionally, MORC2 mutations produce early‐onset spinal muscular atrophy‐like (SMA‐like) phenotypes characterized by proximal muscle and atrophy without sensory loss with or without diaphragmatic palsy, microcephaly, or cerebellar atrophy." (PMID 35904125, 2022). "Missense mutations in MORC2 cause neuropathies including spinal muscular atrophy and Charcot–Marie–Tooth disease." (PMID 29440755, 2018). "However, MORC2 variants are clinically heterogeneous with phenotypes that can be characterized by congenital or early-onset spinal muscular atrophy like or pure motor axonal neuropathy." (PMID 37519884, 2023). "Although CMT is known as a disease associated with peripheral neuropathy, MORC2 mutations cause clinical symptoms such as severe axonal polyneuropathy, spinal muscular atrophy, cerebellar ataxia, diaphragmatic paralysis, craniofacial dysmorphism and nocturnal hypoventilation." (PMID 34695197, 2021). "MORC2 cause diverse disorders depending on the location of the single nucleotide polymorphism, including axonal neuropathy (CMT2Z), spinal muscular atrophy (SMA), developmental delay, impaired growth, dysmorphic facies, axonal neuropathy (DIGFAN), and cancer." (PMID 40760337, 2025). "Sirtuin 2 protects spinal muscular atrophy and Charcot-Marie-Tooth disease by regulating the deacetylation of microrchidia 2 (MORC2), an effector of epigenetic silencing." (PMID 35813508, 2022). "There are several SNPs in the human MORC2 gene, but spinal muscular atrophy is only reported in patients with the p.T362R (p.T424R) and p.S87L mutations." (PMID 34695197, 2021). "MORC2-related axonal CMT disease was first described in 2016 as later onset CMT2 or early onset spinal muscular atrophy-like phenotype." (PMID 34059105, 2021).
axonal neuropathy (9 papers, 2021 to 2025). Any nerve disorder affecting the axon of a nerve. "MORC2 mutations can also manifest as developmental delay, impaired growth, dysmorphic facies, and axonal neuropathy (DIGFAN)." (PMID 39143067, 2024). "Charcot-Marie-Tooth disease type 2Z is caused by MORC2 mutations and presents with axonal neuropathy." (PMID 39143067, 2024). "Recently, 20 individuals with heterozygous MORC2 mutations sharing common features such as developmental delay, impaired growth, facial dysmorphism, and axonal neuropathy were identified in large cohorts of patients with neurodevelopmental disorders." (PMID 35722617, 2022). "Recently, 20 individuals with heterozygous MORC2 mutations were shown to develop a neurodevelopmental syndrome associated with intellectual disability, growth retardation, facial dysmorphism, and axonal neuropathy (DIGFAN; MIM# 619090)." (PMID 35904125, 2022). "In turn, MORC2 is considered a causative gene of CMT with axonal neuropathy; thus, the diagnosis of central neuropathy was omitted in most clinical diagnoses in these patients." (PMID 34695197, 2021). "Charcot–Marie–Tooth disease type 2Z (CMT2Z) is an inherited axonal neuropathy caused by haploinsufficiency of microrchidia CW-type zinc finger protein 2 (MORC2), which leads to elevated hydroxyl radical levels, reduced ATPase activity, and apoptosis-mediated neuromuscular degeneration." (PMID 40760337, 2025). "This mouse model develops axonal neuropathy, locomotor dysfunction, skeletal muscle weakness but also cerebellar ataxia and motor neuron degeneration, thus recapitulating the features of central and peripheral neuropathies associated with MORC2 mutations in humans." (PMID 35722617, 2022). "More recently heterozygous MORC2 variants were found in individuals with DIGFAN syndrome (Developmental delay, impaired growth, dysmorphic facies, and axonal neuropathy), and endocrine abnormalities were observed in some patients." (PMID 38822427, 2024). "MORC2 missense is also considered a causing factor of developmental delay, impaired growth, dysmorphic facies and axonal neuropathy (DIGFAN; OMIM 619090), and CMT2Z and DIGFAN often overlap in their clinical symptoms." (PMID 34695197, 2021).
Charcot-Marie-Tooth disease (9 papers, 2018 to 2025). An inherited degenerative disorder involving the peripheral nerves. "The functional importance of MORC2 in human diseases is highlighted by the fact that its mutations have been linked with Charcot-Marie-Tooth disease, neurodevelopmental disorder, and cancer." (PMID 34974534, 2022). "MORC2 variants are also found in neurological disorders like Charcot-Marie Tooth disease." (PMID 40593625, 2025). "MORC family CW-type zinc finger 2 (MORC2) is a newly identified chromatin-remodeling enzyme involved in DNA damage response and gene transcription, and its dysregulation has been linked with Charcot-Marie-Tooth disease, neurodevelopmental disorder, and cancer." (PMID 34974534, 2022). "Mutations in MORC2 cause axonal Charcot-Marie-Tooth disease (CMT) in humans." (PMID 29329290, 2018).